BRAF (B-Raf proto-oncogene, serine/threonine kinase)
Diseases named in the same sentence as BRAF in open-access papers (continued):
Sharing a sentence is not in itself a finding about the gene and the disease.
melanoma (continued). "We compared the expression level of AC004540.4 in biospecimens collected from healthy, non-cancerous skin samples banked in the GTEx database (n = 1,305 patient tissues), versus the collection of NRAS- or BRAF- mutated melanoma tumors available in the TCGA database (n = 366 patient tissues)." (PMID 38383439, 2024). "Contrary to data indicating an overall incidence of 2%, this could be attributed to the fact that patients with an occult melanoma inherently present at a higher tumor stage, thereby warranting an indication for BRAF mutation analysis." (PMID 39125519, 2024). "RCTs have examined whether BRAF/MEKi or niv/ipi is the best first‐line treatment for BRAF‐mutated melanoma." (PMID 38087810, 2024). "This work is focused on the analysis of FER1L4 (Fer-1 like family member 4 pseudogene; named also as C20orf124) transcript in human primary epidermal melanocytes and melanoma cell lines with different BRAF mutation status, as well as in melanoma patients based on the TCGA dataset." (PMID 39764216, 2024). "Interestingly, the phosphoinositol-3-kinase (PI3K)/AKT pathway is often associated with resistance to BRAF inhibitors in melanoma." (PMID 39086722, 2024). "In addition to the BRAF V600E/K mutant lines, Belvarafenib also inhibited most melanoma lines with a NRAS hotspot mutation (specifically Q61R, Q61K, Q61V, and Q61L) or the wild type for RAS/RAF proteins." (PMID 39199684, 2024). "A mutation in the BRAF oncogene characterizes the BRAF melanoma subtype (B-Raf proto-oncogene)." (PMID 39340537, 2024). "Concerning BRAF mutated melanoma, the COMBI-d and COMBI-v (dabrafenib plus trametinib), BRIM-7 (vemurafenib/cobimetinib), and COLUMBUS (encorafenib/binimetinib) trials, testing the different BRAFi/MEKi combinations, showed five-year survival rate of 34-39% 25-27." (PMID 38164270, 2024). "Of note, most co-occurring mutations in melanoma BRAF Class 2 and 3 (KMT2A, NOTCH1, APC) are of unknown significance, whereas those in Class 1 are amplifications and putative drivers such as NOTCH2 and MET amplifications." (PMID 38275886, 2024). "However, the high incidence of BRAF-mutated melanomas has been observed in fair-skinned individuals in countries such as the USA and Australia." (PMID 38183457, 2024). "The results of coBRIM and COLUMBUS studies were similar, suggesting that BRAF/MEKi alone may be able to maintain long‐term response in selected patients with BRAF‐mutated melanoma." (PMID 38087810, 2024). "Similarly, the combination of vemurafenib and the MEK1/2 inhibitor cobimetinib has been approved for the treatment of unresectable or metastatic melanomas with BRAF V600E and V600K mutations." (PMID 38539548, 2024). "Hence, if the majority of nevi are BRAF-mutated, melanomas have only around 50% of BRAF mutation present." (PMID 38396984, 2024). "Our goal was to determine if metabolic changes produced by the altered signaling pathway due to BRAF mutations differ in the melanoma models and whether these differences correlate with response to treatment." (PMID 38254853, 2024). "Thus, the COMBI-AD trial (NCT 01682083) evaluated 12 months of treatment based on adjuvant therapy with dabrafenib plus trametinib or with placebo in patients with resected stage III melanoma with BRAF V600 mutations." (PMID 39727691, 2024). "The most prevalent mutation in melanoma patients is the BRAF V600E mutation." (PMID 38672652, 2024). "In addition, we observed a positive correlation between the susceptibility of melanoma cells to BRAF/MEK inhibition, as well as cisplatin treatment, and their protection by neutrophils." (PMID 38730718, 2024). "However, BRAFi, such as vemurafenib, dabrafenib, and encorafenib, primarily used to treat BRAF-mutated cancers, particularly melanoma, have been found to have unintended off-target effects on endothelial cells, leading to significant vascular complications." (PMID 39582535, 2024). "In 2002, it was reported that BRAF V600E mutation is frequently found in melanoma." (PMID 38087810, 2024).
melanoma (continued). "Inhibition of polyamine biosynthesis may provide effective synergistic therapy generalizable for diverse tumor types other than melanoma with BRAF mutations." (PMID 38965534, 2024). "Notably, the finding that BRAF mutations are common in about 40–50% of melanoma patients has spurred a renaissance of interest in this sector." (PMID 39195270, 2024). "Furthermore, the miRNA miR-204 was shown to inhibit AM cell motility by targeting AP1S, which gives therapeutic opportunities in BRAF-mutated melanoma." (PMID 39519055, 2024). "In this single-center prospective study, we compared the performance and clinical relevance of a rapid, fully automated real-time PCR assay (IdyllaTM system) with NGS as the standard procedure at our clinic in a cohort of 51 melanoma patients with an indication for BRAF mutation testing." (PMID 39125519, 2024). "Assess if patients with BRAF mutations exhibit dermoscopically similar melanomas." (PMID 38481925, 2024). "Therefore, therapy with MEKi seems to be a logical consequence for BRAF WT melanomas with a mutation-activated MAPK pathway." (PMID 38263136, 2024). "BRAF is the most common driver mutation in melanoma, seen in about 40–60% of all patients." (PMID 39207855, 2024). "This means that tumor types or patient cases in which the most predictive omics feature for a given targeted therapy is a point mutation are currently beyond the scTherapy approach; for instance, melanomas harboring BRAF-V600E mutation are known to benefit from BRAF inhibitors such as vemurafenib." (PMID 39362905, 2024). "BRAF mutations occur in 60% of melanomas and NRAS mutations occur in 15%–20% of melanomas." (PMID 38586368, 2024). "Additionally, tumors with NF1 loss share a pan-cancer RAS pathway activation RNA signature with tumors that have mutations in RAS family genes, including melanomas with BRAF mutations." (PMID 39016685, 2024). "Additionally, melanomas treated with BRAF inhibitors tend to accumulate mutations in NRAS or MEK1/2, exhibiting excessive activation of ERK1/2 or SFK-STAT3." (PMID 38396984, 2024). "Notably, ABCB5 expression at mRNA and protein levels was increased in cell lines resistant to vemurafenib, a molecule targeting the BRAF-activating mutation V600E used in the treatment of melanoma." (PMID 39267923, 2024). "Hence, the knockdown of laminB1 enhanced the response of the BRAF-mutated melanoma to PLX4720 through the cooperative regulation of apoptosis enhancement and autophagy suppression." (PMID 39682248, 2024). "Moreover, mutations in the BRAF gene in melanoma are accompanied by elevated levels of immunosuppressive elements in the immune system, thereby posing an additional challenge to effective personalized immunotherapy for managing the disease." (PMID 39336897, 2024). "Furthermore, some studies with reports of low incidence of BRAF mutations include heterogenous melanoma populations including those with mucosal melanomas which are well documented to typically have a different molecular profile." (PMID 38183457, 2024). "This mutation is present in over 90% of BRAF-positive melanomas." (PMID 38396984, 2024). "Therefore, further phase II and III studies evaluating trametinib against melanoma successfully focused on BRAF-mutated melanoma." (PMID 38263136, 2024). "However, systematic prognostic analysis of CTHRC1 and its relation to the BRAF(V600E) mutation in human colon cancer, thyroid cancer, and melanoma still needs further investigation." (PMID 39052013, 2024). "We observed the benefit of the combination of protein tumor marker S100B and ctDNA BRAF oncogene in preoperative as well as postoperative peripheral blood samples for identification of patients with resectable melanoma (stage I–III) in high risk of recurrence and unfavorable prognosis." (PMID 39387479, 2024). "The BRAF mutation is found in 60% of melanoma cells and 90% of melanoma patients." (PMID 39349424, 2024).
melanoma (continued). "Although the implications of BRAF mutations in the pathogenesis of solid cancers (especially melanoma) are well established and BRAF inhibitors are already in clinical use for patients with melanoma and other malignancies, the role of BRAF in hematological malignancies is still underexplored." (PMID 38254847, 2024). "Notably, BRAF mutations are seen at particularly high rates in melanoma, colorectal cancer (CRC), lung cancer, and papillary thyroid carcinomas (PTCs)." (PMID 38539548, 2024). "Moreover, we reanalyzed the RNA sequence data of the GEO database, and found that 65% of the BRAF-mutation melanoma patients (11 out of 17) gave rise to an upregulated mRNA level of laminB1 after treatment of BRAFi, PLX4720." (PMID 39682248, 2024). "Redox metabolic rewiring has been implicated in BRAF/MEK‐resistant melanomas." (PMID 39494561, 2024). "Therefore, as an initial genetic alteration in nevus-to-melanoma evolution, BRAF mutation can be predicted by the association of CM with a nevus, especially in patients with CM located at the trunk (nonsun-exposed skin)." (PMID 39735251, 2024). "In addition to melanoma, colorectal cancer and thyroid cancer are also known to frequently carry BRAF mutations." (PMID 38965534, 2024). "Given the prominent role of MAPK signaling in BRAF-mutant melanomas we decided to assess whether miR-579-3p expression levels may be linked to BRAF mutational status." (PMID 38472212, 2024). "It should be mentioned that melanomas with BRAF V600K mutation present several peculiarities." (PMID 38391404, 2024). "UV Response pathways were significantly enriched in Class 2/3 mutants vs. BRAF Class 1 melanomas, which could explain the increased tumor mutation burden in these tumors." (PMID 38275886, 2024). "A low level of BRAF mutations (25%) has also been found among Scottish melanoma patients." (PMID 38183457, 2024). "In patients with co-occurring cancers with a high frequency of BRAF mutations, such as melanoma and carcinoma of the colorectal region, BRAFV600E positivity may not be diagnostic." (PMID 39336882, 2024). "Similarly, mutations in BRAF, such as the V600E mutation commonly found in melanoma, can also result in constitutive kinase activity and downstream pathway activation." (PMID 39582535, 2024). "The analysis of BRAF mutation status has become a standard diagnostic procedure for melanoma." (PMID 38891988, 2024). "Furthermore, targeted therapies other than BRAF/MEK inhibitors are needed, particularly for ethnic groups with a lower incidence of BRAF‐mutated melanoma." (PMID 39564955, 2024). "BRAF inhibitors are widely employed in the treatment of melanoma with the BRAF V600E mutation." (PMID 38965534, 2024). "BRAF V600 mutations were identified in 54% of melanomas, and NRAS G12/G13 mutations in 50%." (PMID 38396984, 2024). "Additionally, we provide insights into the complex interactions among BRAF signaling, ICD, and IFN-1 pathway activation, highlighting potential avenues for therapeutic intervention, immunomodulation, and enhancing responses to ICD in BRAF-mutated melanomas." (PMID 39061208, 2024). "Of the 16 patients who did remember, 81% reported that their melanoma harboured a BRAF mutation." (PMID 39624750, 2024). "From this, we hypothesized that they would select subsequent mutations in a different sequential order, specifically melanomas arising from BRAF V600E mutant precursors would first have to override the OIS checkpoint." (PMID 38371417, 2024).
melanoma (continued). "Furthermore, we evaluated the prognostic factors for advanced BRAF-mutated melanoma patients; we found that ECOG PS≥2, presence of liver metastases, and high LDH level from initiation of first-line treatment were all associated with differences in PFS and OS." (PMID 38450188, 2024). "Therefore, there are no treatment options with approval based on data from patients with advanced melanoma who have progressed after one line of ICI therapy for BRAF-WT patients or two lines of therapy for BRAFV600 mutation-positive tumors." (PMID 39727691, 2024). "However, there are negative reports, and at this point it remains to be elucidated why niv/ipi is more effective in BRAF‐mutated melanoma." (PMID 38087810, 2024). "Somatic BRAF mutations occur in about 50% of melanoma patients." (PMID 38893253, 2024). "Melanoma has a high mutation burden, with 70–80% of melanomas having BRAF mutations." (PMID 39195270, 2024). "Compared with patients with BRAF WT melanoma, those with BRAF-mutated melanoma have reportedly been more often younger and have tumors that have a thinner Breslow thickness with superficial spreading or nodular histology and/or in anatomical regions without chronic sun damage." (PMID 38183457, 2024). "For example, Herceptin is used in patients with female breast cancer with HER-2 expression, Imatinib targets the BCR/ABL fusion gene in chronic myeloid leukemia, Vemurafenib targets BRAF mutations in melanoma, and Gleevec inhibits tyrosine kinase activity in chronic myeloid leukemias." (PMID 39767657, 2024). "QMS models generalized from tumor cell lines to melanoma patients treated with BRAF inhibitors, where these models not only outperformed binary mutations but also identified key molecular factors influencing BRAF inhibition." (PMID 38940147, 2024). "Notably, we observe that laminB1 expression is upregulated when BRAF-mutated melanoma cells develop resistance to vemurafenib." (PMID 39682248, 2024). "Interestingly, this distinct regulation pattern of apoptosis and autophagy by laminB1 cooperatively promotes the response of BRAF-mutated melanoma cells to vemurafenib." (PMID 39682248, 2024). "Indeed, the acquisition of a BRAF mutation was suggested to be an initiating event in melanocytic neoplasia, including both nevi and melanoma." (PMID 39735251, 2024). "Notably, the present study also demonstrated that the ICT antibody induced apoptosis in BRAF wild-type Mewo melanoma cells as well as in BRAF-mutated A2058 and G361 cells in the presence of CPI-613/HCQ." (PMID 38434963, 2024). "Notably, RAS mutations are prevalent in 15-30% of all human cancers, while BRAF mutations are found in 30-60% of melanomas, 30-50% of thyroid cancers, and 5-20% of colorectal cancers." (PMID 39582535, 2024). "BRAF mutation is known to be a diagnostic and prognostic biomarker for melanoma." (PMID 39457498, 2024). "Additionally, we demonstrated a strong correlation of melanoma cell susceptibility to dual BRAF/MEK inhibition and the degree of protection in cocultures with neutrophils." (PMID 38730718, 2024). "First-line immunotherapy followed by a switch to targeted BRAF + MEK therapy could be the most beneficial for patients with BRAF-mutated melanoma." (PMID 39684531, 2024). "In some patients, we could also exclusively detect mutations in melanoma driver genes (BRAF, NRAS, MAP2K1, KIT) suggesting that CTC analysis could complement ctDNA analysis for relevant clinical implications in personalized medicine in oncology." (PMID 38898234, 2024). "The impact of adjuvant therapy may also vary based on melanoma subtype and BRAF mutation status, requiring further investigation." (PMID 38212945, 2024). "Additionally, we tested rilmenidine activity in two melanoma cell lines–A-375, derived from female melanoma patient, and Hs 294T, collected from a male patient–both of which carry BRAF mutation." (PMID 38781180, 2024).
melanoma (continued). "Approximately 50% of melanomas have BRAF mutations, with the majority being BRAFV600E, which causes intrinsic activation of the BRAF-MEK-ERK-MAPK signalling pathway, also known as the Mitogen-activated protein kinase (MAPK) pathway, leading to enhanced melanoma cell proliferation and survival." (PMID 38334660, 2024). "Notably, a subgroup analysis of the CheckMate 067 trial demonstrated the benefit of nivo/ipi combination therapy for the BRAF-mutated advanced melanoma group." (PMID 39337055, 2024). "Mutation of BRAF is known to induce melanoma genesis and metastasis." (PMID 39349424, 2024). "We performed a retrospective study on 174 patients with BRAF‐mutated melanoma." (PMID 38491825, 2024). "Targeting BRAF mutations in melanoma has become a significant therapeutic approach." (PMID 38674331, 2024). "Investigating the unfavorable link between peripheral blood neutrophils, in the context of melanoma, and targeted therapy, we firstly examined impairment of viability upon targeted therapy in eleven BRAF-mutated melanoma cell lines and observed varying degrees of sensitivity to treatment." (PMID 38730718, 2024). "Grützner and colleagues demonstrate that in BRAF-mutated melanoma, RIG-I agonist-induced cancer immunotherapy combined with standard-of-care MAP kinase pathway inhibitors dabrafenib and trametinib outperforms the individual therapeutic efficacy of each inhibitor." (PMID 39165562, 2024). "Interestingly in a murine model, the ability to initiate melanoma formation after UVR exposure was higher in NRAS-mutant melanocytes as compared to BRAF-mutant melanocytes, whereas mutational burden was higher in BRAF-driven tumors." (PMID 38672543, 2024). "Therefore, our data suggest that elevated CTHRC1 expression is positively associated with the BRAF(V600E) mutation in colon cancer, thyroid cancer, and melanoma patients." (PMID 39052013, 2024). "For predicting response to systemic therapy in high-stage melanomas, BRAF mutation status must be assessed, either using IHC specific for the V600E mutant protein or using BRAF gene mutation analysis before BRAF-inhibitor and MEK-inhibitor therapy can be initiated." (PMID 38247727, 2024). "carried out a retrospective clinical trial wherein plasma samples from patients receiving vemurafenib for BRAF-mutated melanoma were used to assess the expression of 90 lncRNA that may have an association with the development and growth of cancer." (PMID 39777348, 2024). "For example, a common BRAF mutation observed in melanoma (V600E) regulates oxidative metabolism through peroxisome proliferator-activated receptor–gamma coactivator 1-α (PGC1α) and MITF, linking increased mitochondrial capacity and resistance to oxidative stress." (PMID 39519202, 2024). "Melanoma patients with BRAF mutations have shown favorable responses to ICIs." (PMID 39025927, 2024). "Moreover, TMEM16A functions cooperatively with mutated BRAF to promote malignant melanoma progression by enhancing the proliferation of the cells." (PMID 39070550, 2024). "For example, vemurafenib, which targets mutant BRAF, can lead to dedifferentiation in melanomas, making them more susceptible to ferroptosis, as evidenced by significant changes in lipid composition, including an increase in polyunsaturated fatty acids (PUFAs)." (PMID 38206305, 2024). "Finally, a comparison between the presence of the BRAF mutation and previous diagnoses of primary melanoma was also conducted." (PMID 39200941, 2024). "The primary mutations discussed in melanoma research include BRAF, PTEN, and NRAS mutations." (PMID 38835341, 2024). "One hundred and six BRAF mutated advanced melanoma patients were identified." (PMID 39207855, 2024). "NF1 + melanomas constitute about 12–23% of melanoma patients and are characterized by the highest mean rate of mutations (39 mutations/MB), stronger than BRAF + subtype UV signature correlation, and worst overall survival." (PMID 39340537, 2024).